LINC00652 (long independently transcribed non-coding RNA 652)
Synonyms: HSPC072
Gene: Long non-coding RNA gene on chromosome 20 (18,786,065 to 18,794,584, reverse strand). Ensembl gene ENSG00000179935.
Diseases named in the same sentence as LINC00652 in open-access papers:
LINC00652 is named in the same sentence as 1 disease in open-access papers, as found by Europe PMC text mining. Sharing a sentence is not in itself a finding about the gene and the disease. The quoted sentences say what the papers report.
myocardial ischemia (1 paper, 2021). A disorder of cardiac function caused by insufficient blood flow to the muscle tissue of the heart. "There were rare studies that investigate the roles of LINC00652, except one that analyzed its functions in myocardial ischemia-reperfusion injury: LINC00652 was found to be overexpressed in the myocardial cells of mice with myocardial ischemia-reperfusion injury." (PMID 34211824, 2021).